ARG1 (arginase 1)
Diseases named in the same sentence as ARG1 in open-access papers (continued):
Sharing a sentence is not in itself a finding about the gene and the disease.
infection (continued). "Consistently, Arginase-1 overexpression led to an increase in the numbers of parasites per vacuole in ME49wt infection group." (PMID 40394721, 2025). "Gene expression analysis showed distinct metabolic shifts, including upregulation of arginase-1 (Arg1) and proline metabolism genes, with concurrent suppression of nitric oxide synthase 2 (Nos2) in the brain during the late infection phase." (PMID 41258798, 2025). "As an essential amino acid, L-arginine can not only modulate the host cellular immune response during pathogen infection, but also as a shared substrate for iNOS and Arginase-1." (PMID 40394721, 2025). "Subsequently, we analyzed the expression of INOS and ARG1, which are well-known markers of M1 and M2 macrophage phenotypes, respectively, in lung homogenates on day 3 post-infection using Western blotting." (PMID 38675960, 2024). "MAC-infected BMDMs underwent the dramatic induction of inflammation genes such as cytokines and chemokines 4 h after infection, although Arg1, an M2 marker gene, continued to be upregulated 24 h after infection." (PMID 38711507, 2024). "Transcriptional profiles of the genes CD38, Gpr18, Fpr2 (markers of classically activated macrophages), Arg1, and Egr2 (markers of alternatively activated macrophages) are significantly activated after infection with all viruses." (PMID 38473707, 2024). "Contrarily, the infection of AAMΦ with the less virulent T. cruzi isolate (CI2) resulted in a similar Arg-1 expression compared to the one observed in uninfected AAMΦ." (PMID 39452749, 2024). "The results showed that the expression levels of iNOS and TNFα were decreased in KCs at 2 months post-infection, while Arg1 was obviously increased." (PMID 38553755, 2024). "There was a reduction of ARG1+F4/80+ cells in the gut of T.mu-colonized mice post infection, while the iNOS+F4/80+ cells were similar between the T.mu-colonized and T.mu-uncolonized mice." (PMID 38565558, 2024). "The expression level of the Arg1 gene was increased significantly at chronic infection (30 dpi) compared to acute infection (3 dpi–9 dpi)." (PMID 39497817, 2024). "Regarding Arg-1, infection of BMMΦ with the QRO isolate significantly induced Arg-1 expression and activity in AAMΦ, which resulted in a higher parasite load than the one in the unstimulated BMMΦ." (PMID 39452749, 2024). "In conclusion, our results highlight the important role of L-arginine metabolism through NOS2 and Arg-1/2 during infection with T. cruzi." (PMID 39452749, 2024). "In macrophages, resident macrophages, and dermal dendritic cells, Nos2 and Arg1 involved in nitric oxide metabolism were upregulated genes after infection." (PMID 39536069, 2024). "In line with an earlier report, we found that the expressions of both types of arginase, Arg-1 and Arg-2, in the murine spleen were increased by STm infection." (PMID 39102375, 2024). "Our results showed that T.mu-colonized mice upregulated intestinal Nos2, Otc, and Ass1 expression, while downregulated Arg1 expression post infection, compared to the C. difficile-infected T.mu-free control mice." (PMID 38565558, 2024). "Throughout the first 8 weeks, liver protein levels of the M1 macrophage marker iNOS and the M2 macrophage marker Arg-1 significantly increased, suggesting a synergistic role for both macrophage types during the initial infection phase." (PMID 39749332, 2024). "We found that infection of macrophages with S.tm resulted in increased mRNA and protein expression of Arg1 and iNos in F4/80+CD11b+ macrophages." (PMID 37190073, 2023). "Macrophages pre-primed with IFNγ showed slightly higher levels of Arg1 mRNA upon infection compared to unpolarised infected macrophages treated with IFNγ after onset of infection." (PMID 37190073, 2023).
infection (continued). "Macrophages and supernatants were collected after different times (0h, 4h, 12h, 24h and 48h) of B. abortus-infection, and mRNA expression of macrophage M1 (Tnfα, Nos2 and Il1β) and M2 (Tgfβ, Arg1, Il10) polarization marker genes were detected by RT-qPCR." (PMID 37325614, 2023). "Meanwhile, we found that Arg-1 expression was upregulated in the hippocampus and HT-22 cells of mice after TgCtwh3 infection and that it decreased in response to DFP." (PMID 37651502, 2023). "Several studies have shown that changes in iNOS and ARG1 expression are detrimental to the outcome of specific infections." (PMID 37190073, 2023). "The higher levels of Chil3 and Arg1 transcripts in K101R-infected mice suggested stronger immune responses during the course of infection compared to WT, partly due to increased replication and enhanced neurovirulence for mice." (PMID 37884553, 2023). "In murine macrophages, it has been demonstrated in vitro that ARG1 is produced soon after infection and can have immunomodulatory effects." (PMID 37078586, 2023). "We observed reduced levels of Arg1 upon putrescine supplementation (arg+/put+ or put+) after 4h of incubation or infection compared with arg+spd+, spd+, and arg+/spm+." (PMID 37000792, 2023). "RAW264.7 cells from each group were collected at 24 h after infection and analyzed for iNOS and ARG1 mRNA expression using qPCR." (PMID 37628738, 2023). "While macrophage 1 (M1) produces proinflammatory cytokines and NO and fights infection, M2 macrophages are permissive host cells that express arginase 1 and play a role in tissue repair." (PMID 37662946, 2023). "The results revealed a significant increase in the relative expression levels of Arg1 mRNA in liver tissues at 12 weeks post‐infection compared with the uninfected controls (p < 0.05)." (PMID 37430471, 2023). "On the other hand, the resistance to infection by the helminth Trichuris muris is unaffected by the deletion of Arg1 in macrophages suggesting more complex roles of arginine metabolism during helminth infection." (PMID 35154105, 2022). "Arg1, one of the marker genes of M2 macrophages, also began to increase significantly at 30 days after infection." (PMID 36169259, 2022). "Arg-1, the enzyme for metabolizing arginine to ornithine and thereby reducing extracellular arginine at sites of infection, was slightly increased in infected cells at 4 h, followed by a 2.5-fold and one-fold upregulation at 10 and 18 h, respectively." (PMID 36618364, 2022). "Violin plots show that Kp52145 infection increased the levels of the M(Kp) markers arg1, il10, chi3l1, ido, pparγ, mrc1, nos2, isg56 and il1rn (Fig EV5A–E)." (PMID 36337046, 2022). "More importantly, we showed that adoptive transfer of Clec2d-deficient MDSCs induced by GM-CSF plus GXM into wild-type mice significantly decreased their pulmonary fungi burden and Arg1 expression after infection with C. neoformans hypocapsular strain Cap59." (PMID 35835754, 2022). "Heterologous infection with RV-A1B and RV-A2 increased F4/80+/CD11c+/arginase-1+ cells compared to RV-A1B alone." (PMID 36032072, 2022). "The results of the present study showed that the expression level of iNOS significantly increased in dMφ after infection with T. gondii, both in vitro and in vivo, while the expression of Arg-1 decreased." (PMID 36514159, 2022). "RV-A1B infection on day 6 of life increased lung F4/80+/CD11c+/arginase-1+ cells compared to sham infection." (PMID 36032072, 2022). "On the other hand, the Slc7a1 L-arginine transporter was downregulated during the infection, and Nos2, Arg1, Odc1, and Slc7a2 were expressed at similar levels in uninfected macrophages." (PMID 35202090, 2022). "Transcriptomics analyses in the hamster model of infection have identified mRNAs for regulatory cytokines (IL-4, IL-10, and IL-21), arginase (Arg1), and low nitric oxide production by macrophages as key factors of immunopathology and parasite persistence." (PMID 35384718, 2022).
infection (continued). "IFNγ treatment resulted in lower urea concentrations, nicely resembling the effects of cytokines and infection on Arg1 expression." (PMID 34359992, 2021). "Accordingly, the induction of ARG1 has been linked to an increase in tissue pathogen loads in the case of infections with Leishmania, Trypanosoma or Mycobacteria spp., whereas the inhibition or deletion of ARG1 led to improved infection control by the host." (PMID 34359992, 2021). "Infection with S.tm induced Arg1 expression and IL-4 had an additive effect, whereas IFNγ reduced Arg1 mRNA expression." (PMID 34359992, 2021). "For studying the effect of ARG1 on the control of infections with Salmonella, we used the Tie2Cre+/−ARG1fl/fl mouse model." (PMID 34359992, 2021). "We confirmed our findings obtained with the Tie2Cre mouse model by performing infection experiments, in which we blocked ARG1 using the orally bioavailable inhibitor CB-1158, which yielded similar results." (PMID 34359992, 2021). "So far, only little information has been available on the regulation of ARG1 upon infection with the intracellular bacterium S.tm and on a potential impact of ARG1 on the control of S.tm infection." (PMID 34359992, 2021). "With regard to gene expression analysis by overlapping along infection, transcripts deemed relevant to VL, such as ARG1 and IDO1, exhibited high expression at 60, 120 and 150 dpi." (PMID 34804009, 2021). "During L. major infection in vivo, HIF-1α and HIF-2α, as well as multiple HIF-1α and HIF-2α targets, including Vegfa, Nos2, and Arg1, are elevated at the site of infection." (PMID 34959539, 2021). "Both at 4 and 14 h after infection, Arg1 expression was higher in infected BMDM of C57BL/6N than in infected BMDM of NRAMPG169 C57BL/6N mice." (PMID 34359992, 2021). "Peritoneal macrophages from STAT1+/+ and STAT1−/− recruited at 8 weeks post-infection were analyzed for the expression of Arginase-1, Fizz1, and Ym1." (PMID 34684235, 2021). "In the second phase of the immune response to pathogen infection, Arg1-expressing macrophages dominate in response to Th2-type cytokines and provide Pro and polyamines that participate to modulate the hyperinflammation and to tissue repair." (PMID 34163018, 2021). "Herein, we investigated the role of ARG1 during infection with Salmonella enterica serovar Typhimurium (S.tm)." (PMID 34359992, 2021). "The results also showed a second peak of macrophage infiltration in the C57BL/6 mice after 240 h of infection, with higher Arg-1 and CD206 marking than BALB/c." (PMID 34660334, 2021). "The competition between iNOS and ARG1 for L-arginine has also been shown to be highly relevant for the control of infections with intracellular bacteria, such as M. tuberculosis, which are sensitive to NO-mediated killing." (PMID 34359992, 2021). "This study provide important data showing increased expression of ARG-1 in peritoneal cells after Eg-PSC infection." (PMID 32029006, 2020). "The ILC2s of Cluster 14 expressed Cor1a, Samhd1, Ccl1 (monocyte chemotaxis), Arg1 (promotes acute type 2 inflammation), and C1qbp (involved in multiple infection and inflammatory responses)." (PMID 32351546, 2020). "During the late stages of infection, ARG1 contributes to control of prolonged hyperinflammation; ARG1 also plays a role in regulating the progression of lung immunopathology in Mtb-infected, Nos2-deficient mice." (PMID 32903583, 2020). "The profiles of ARG-1 expression in peritoneal cells and CD3ζ expression in T cells from spleens were assessed at different time points (3, 6, 9 and 12 months post-infection) by flow cytometry." (PMID 32029006, 2020). "Conversely, arginase 1, the cytoplasmic isoform of arginase which Mtb is known to specifically drive in infection, inhibits NO synthesis through several proposed mechanisms including competing with NOS for arginine as a substrate." (PMID 32984072, 2020).
infection (continued). "To confirm these results, we performed immunohistochemical analysis of ARG1 and iNOS proteins in footpad sections from LmJ3OE- and LmMC-infected mice at 23 and 44 days post-infection." (PMID 33114674, 2020). "By contrast, the Th2 cytokine IL-4 promotes M2/alternatively activated macrophages, which express arginase-1 and shelter infection." (PMID 32477357, 2020). "At initial stages of infection, the Mtb pathogen takes advantage of ARG1 activity by limiting macrophage immunity via competition with iNOS/NOS2." (PMID 32903583, 2020). "Taken together, these data verified that ARG-1 is upregulated in multiple peritoneal cells after Eg-PSC infection and exhibits a gradually rising trend prior to 9 months." (PMID 32029006, 2020). "At day 44 post-infection, the value of ARG1 staining was similar in footpad sections from both the LmJ3OE- and LmMC-infected mice." (PMID 33114674, 2020). "In contrast, these macrophages displayed a decreased expression of the M2 markers such as Arg1, Ym1, and Mrc1 (mannose receptor C-type 1) at 24 h post-infection." (PMID 31801478, 2019). "It is clear that macrophages participate in many important immune functions following infection with helminths that are characterized by M2 signature molecules (e.g. including Arg1, FIZZ1, and Ym1)." (PMID 31810203, 2019). "We believe that the patients with chronic inactive gastritis established a mechanism of protection against infection, and with an increase in ARG1, established a modulation process for regeneration." (PMID 31320834, 2019). "PSG recruited host macrophages to the site of infection and manipulated their physiology by upregulating the expression of arginase 1, an enzyme responsible for polyamine production and a signature of macrophage alternative (M2) activation." (PMID 31452467, 2019). "The data showed that the expression of iNOS was significantly elevated while that of Arg-1 was diminished in the macrophages with RHΔrop16 infection when tested by qRT-PCR and Western blotting." (PMID 32082272, 2019). "Our data revealed that melatonin treatment of macrophages promoted modulation of the expression of mRNA involved in L-arginine metabolism during infection, inducing Nos2 to the detriment of Arg1 and thus altering infectivity." (PMID 30949455, 2019). "The comparison between WT and TLR4−/− macrophages revealed decreased levels of the Arg1 and Nos2 transcripts throughout the course of infection (respectively)." (PMID 30555476, 2018). "In contrast, MyD88−/− macrophages showed decreased levels of Arg1 and Nos2 transcripts in all infection periods analyzed (respectively)." (PMID 30555476, 2018). "L-arginine is a semi-essential amino acid needed for cell proliferation, and is the substrate of arginase 1 (Arg-1) and inducible nitric oxide synthase (iNOS), which is involved in the immune response against infections." (PMID 29337988, 2018). "Overall, our results demonstrate that Nrf2, iNOS, and Arg-1 are produced at the site of infection, suggesting a role for them in human TB." (PMID 30428359, 2018). "Our initial findings were also validated in vMC0-infected BN rats, where infection resulted in the induction of genes associated with macrophage M2 activation (MGL1, ARG1, IL10, and IL10RA) and Th2 genes (IL33 and IL25)." (PMID 30150981, 2018). "As we seen in flow cytometry data, we found an increased number of “dual function” iNOS+Arg1+F4/80+ cells during and super-infection in Stat2−/− mice compared to WT mice." (PMID 30337919, 2018). "Ultimately, bacterial control in Stat2−/− mice during super-infection was compromised when the number of iNOS+Arg1+ dual function macrophages was diminished." (PMID 30337919, 2018). "The comparison between WT and TLR2−/− macrophages showed increased levels of the Arg1 transcript 4 h after infection and decreased levels of Nos2 transcript in all infection periods analyzed (respectively)." (PMID 30555476, 2018).
infection (continued). "Analyzing mRNA for components of L-arginine metabolism, we observed that the effect of IL-4 on infection progression was via the increase of Arg1 and Larg mRNAs, while the effect of IL-13 on infection progression was only via the increase in Larg mRNA." (PMID 30150896, 2018). "Together, our data for the first time clearly demonstrate that the induction of Nos2- and Arg1-expressing M-MDSC provides an immune escape mechanism that supports infection and pathology by virulent M. avium subspecies." (PMID 30386330, 2018). "Elevated Mφ-specific arg1 transcripts during infection were confirmed following purification from PC by FACS." (PMID 29547639, 2018). "By measuring the AAMφ product, arginase, we defined that arg1 transcripts and enzymatic activity within peritoneal cells (PC) from B. malayi (Bm)L3 primary infections were significantly enhanced compared with naïve mice." (PMID 29547639, 2018). "Despite the presence of M1 macrophages during Arg1/M2 blockade and M2 macrophages during IFNγ/M1 blockade, bacterial control was suppressed in Stat2−/− mice during super-infection." (PMID 30337919, 2018). "In line with the clinical findings, C57BL/6 IFN-β−/−, IFNAR1−/−, and WT mice exhibited similar mRNA expression levels of IFN-γ, interleukin (IL)-4, IL-12, IL-13, inducible nitric oxide synthase, and arginase 1 during the acute and late phase of the infection." (PMID 29459858, 2018). "The QRT-PCR results showed that the expression of iNOS and IL-12 peaked at day 3 post-infection and then declined, while the expression of Arg1 and IL-10 slowly increased in the first 3 days and rapidly increased in the following days." (PMID 28824565, 2017). "In lungs of LysMcreSOCS3loxP/loxP mice, 1 week after infection Arg1 precedes Nos2 gene expression and accordingly Arg1-positive cells were abundant, whereas NOS2-positive cells were hardly detectable." (PMID 29176982, 2017). "L. amazonensis infection induces the CAT2B, CAT1 and ARG1 expression in BALB/c macrophages enabling the establishment of infection." (PMID 29379478, 2017). "Together, SOCS3 restrains an uncontrolled early expression of Arg1 and is necessary for controlling infection of lung macrophages during experimental TB." (PMID 29176982, 2017). "In the present study, Arg-1 levels were maintained throughout the infection, with the highest level occurring at the fibrotic and cirrhotic stage." (PMID 28542159, 2017). "Helminths can induce AAMs with increased expression of arginase-1 in mice, which can be less capable of combating infection with bacteria, although this kind of type 2 response is needed to expel the helminths." (PMID 28192437, 2017). "Because in Mtb-infected LysMcreSOCS3loxP/loxP mice an elevated arginase activity precedes the increased induction of NOS2 mycobacteria were mostly found in Arg1-expressing cells at early time points of infection." (PMID 29176982, 2017). "After 4 h of infection with La-WT L. (L.)amazonensis, the host Nos2 expression was not altered, but we observed up-regulated expression of host Arg1 mRNA." (PMID 28276497, 2017). "Conversely, the expression of Arg-1, an M2-specific enzyme, increased from 7 weeks after infection and was markedly upregulated 10–12 weeks postinfection." (PMID 28542159, 2017). "Our findings demonstrate that type I IFN induces Nos2 and inhibits Arg1 expression following infection of macrophages with M. tuberculosis, resulting in high NO production by infected macrophages." (PMID 27849167, 2016). "This revealed that macrophage-derived type I IFN suppressed Arg1 induction in infected macrophages, because Arg1 levels were significantly higher in Ifnar−/− macrophages than in WT macrophages at 6 h post–BTB 02-171 infection." (PMID 27849167, 2016). "Our previous work identified the helminth-antibody-driven activation of Arg1 expressing MΦ as an important mechanism to limit tissue disruption at early timepoints following repeated infection with the intestinal nematode Hpb." (PMID 25806513, 2015).